PTH (parathyroid hormone)
Diseases named in the same sentence as PTH in open-access papers (continued):
Sharing a sentence is not in itself a finding about the gene and the disease.
hypoparathyroidism (continued). "R 6.2 - We recommend against the use of recombinant PTH for hypoparathyroidism." (PMID 36149449, 2022). "Hypoparathyroidism (HypoPT) is caused by the chronic deficiency or absence of parathyroid hormone (PTH)." (PMID 36382753, 2022). "Chronic hypoparathyroidism is a rare disease caused by absent or insufficient production of parathyroid hormone (PTH)." (PMID 36389126, 2022). "TransCon PTH is a once-daily long-acting prodrug of PTH for adult hypoparathyroidism treatment." (PMID 36382754, 2022). "Ideally, the treatment of hypoparathyroidism replaces the absence or insufficiency of PTH." (PMID 34820344, 2021). "None of the comparative studies found a statistically significant relationship for postoperative PTH levels between study and control groups, except for, which found a statistically significant lower incidence of transient hypoparathyroidism in the NIRAF group (33.7% vs. 46.6%; p = 0.002)." (PMID 34359693, 2021). "Hypoparathyroidism is a rare endocrine disorder caused by absent or inappropriately low levels of parathyroid hormone (PTH)." (PMID 33599907, 2021). "PTH can already been determined 20 mins after TT and cut-off values of <15 pg/mL or <20 pg/mL, also depending on the assay used, can help to predict the likelihood of therapy-relevant postoperative hypoparathyroidism." (PMID 35071309, 2021). "When compared with other PHPT patients, PC patients were more frequently male and had higher preoperative blood calcium and PTH and lower phosphate levels, larger and heavier parathyroids excised, lower postoperative calcium, and a higher rate of postoperative hypoparathyroidism." (PMID 34659402, 2021). "However, the PTH level gradually recovered within 6 months after surgery in most cases, with five patients (1%) experienced permanent hypoparathyroidism." (PMID 33746905, 2021). "Because low vitamin D level increases serum PTH level, and some patients with low vitamin D level might be excluded from the hypoparathyroidism even though they had actual hypoparathyroidism." (PMID 34640472, 2021). "Compared with other PHPT patients, PC patients were more frequently male, had higher preoperative blood calcium and PTH and lower phosphate, had larger and heavier parathyroids excised, had lower postoperative calcium levels, and showed a higher rate of postoperative hypoparathyroidism." (PMID 34659402, 2021). "The predictive utility of day 1 postoperative PTH levels may be limited to transient hypoparathyroidism." (PMID 33498810, 2021). "Postoperative hypoparathyroidism (PTH <3 pg/ml) was found in 22 patients (21.2%)." (PMID 34552559, 2021). "Variations of serum magnesium levels, both hyper and hypomagnesemia, may deregulate secretion of PTH, culminating in a reversible hypoparathyroidism." (PMID 35036185, 2021). "PTH levels <15 pg/mL at least 20 mins or more following TT might predict potential therapy-relevant hypoparathyroidism." (PMID 35071309, 2021). "The definition of permanent hypoparathyroidism varies in the literature and often comprises three primary domains: a quantitative domain based on PTH level, a qualitative domain based on clinical features or activated vitamin D requirement, and a temporal domain based on time since operation." (PMID 33498810, 2021). "This current study found no significant between-group difference in the incidence of permanent hypoparathyroidism (8.3% vs. 8.5%; p ≥ 0.99), suggesting that day 1 PTH < 10 pg/mL may only be predictive of transient hypoparathyroidism." (PMID 33498810, 2021). "This blunted PTH response has been termed “functional hypoparathyroidism”." (PMID 34580590, 2021). "Day 1 hypoparathyroidism was defined as a PTH level < 10 pg/mL." (PMID 33498810, 2021). "Post-TT hypoparathyroidism induces a decrease in circulating levels of parathyroid hormone (PTH)." (PMID 33628238, 2021).
hypoparathyroidism (continued). "Hypoparathyroidism (HP) is a rare endocrine disorder characterized by absent or inappropriately low levels of circulating parathyroid hormone with associated significant physical and cognitive symptoms." (PMID 34374868, 2021). "Postmenopausal women with functional hypoparathyroidism exhibit higher bone mineral density than women with an elevated PTH response and, hence, may have lower fracture risks." (PMID 34580590, 2021). "If effective, this oral PTH analogue could overcome concerns about injectable use and be a future treatment option for hypoparathyroid patients." (PMID 32765831, 2020). "Hypoparathyroidism is a rare endocrine disorder characterized by inappropriately low or absent levels of PTH associated with hypocalcemia and hyperphosphatemia." (PMID 32398014, 2020). "The postoperative serum calcium and blood PTH levels as well as the incidence of postoperative transient hypocalcemia were compared between the two groups in order to confirm whether the PTH-ICGT assay could prevent the occurrence of hypoparathyroidism." (PMID 33967947, 2020). "Interestingly, the gestational maternal parathyroid hormone levels were in normal ranges (31-37 pg/ml during the pregnancy), yielding the diagnosis of idiopathic primary neonatal hypoparathyroidism." (PMID 33062471, 2020). "A low PTH level in hypoparathyroidism induces high phosphate levels, and treatment with high-dose calcium and active vitamin D may increase the calcium-phosphate product, which can induce calcium-phosphate crystal formation in the lens of the eyes." (PMID 32384131, 2020). "On the other hand, hypoparathyroidism (hypoPT) is a less common parathyroid gland disorder, characterised by low calcium levels in the blood serum due to inadequately low parathyroid hormone (PTH) levels." (PMID 32155210, 2020). "This study was a case-control cross sectional study, which could be better if we design an interventional clinical trial to evaluate the effect of PTH in hypoparathyroid patients in the future." (PMID 32398014, 2020). "Treatment of hypoparathyroidism with intermittent PTH injections has been an important advance." (PMID 32765831, 2020). "Such a continuous calcium sensor in combination with PTH delivery by a pump device could constitute a transformative closed-loop “artificial parathyroid” system for hypoparathyroid patients." (PMID 32765831, 2020). "Hypoparathyroidism results from low parathyroid hormone (PTH) levels." (PMID 32612651, 2020). "However, it has been described that excessive suppression of PTH, or relative hypoparathyroidism, leads to a decrease in bone remodelling or adynamic bone." (PMID 31138150, 2019). "Conventional therapy consists of calcium and active vitamin D. PTH replacement therapy has been demonstrated to lower the doses of calcium and active vitamin D required and may lower the long-term complications of hypoparathyroidism." (PMID 30540559, 2019). "Such a decreased level of calcium is associated with hypoparathyroidism, nonresponsiveness of target organs to PTH, vitamin D metabolism disorders, hyperphosphatemia, hypomagnesemia, and hypercalcitonemia in the first days of life." (PMID 31320908, 2019). "Although this approach can correct the hypocalcemia associated with hypoparathyroidism, it does not replace other functions of PTH and can lead to or worsen hypercalciuria." (PMID 31369089, 2019). "Thus, the term “hypoparathyroidism” is commonly reserved to describe a situation in which the parathyroid glands are unable of properly producing PTH (A)." (PMID 29694629, 2018). "Hypoparathyroidism may also result from deregulation of PTH secretion secondary to disorders of magnesium homeostasis or abnormal activation of CaSRs due to a genetic or autoimmune cause." (PMID 29694629, 2018). "Finally, all prior studies of PTH replacement therapy in hypoparathyroidism have shown that HRQoL at baseline (i.e., while receiving conventional therapy) was lower than in the general population." (PMID 29099947, 2018).
hypoparathyroidism (continued). "The “blunted PTH response” may correspond to a protective mechanism of bone mass, through the development of a functional hypoparathyroidism." (PMID 29149839, 2017). "If hypoparathyroidism is present, recombinant human parathyroid hormone (rhPTH, Natpara), commercially available in the United States, may be indicated." (PMID 28730291, 2017). "Conversely, hypoparathyroidism refers to an insufficient production of PTH." (PMID 27694822, 2016). "The PTH value was divided into 2 level: <15 pg/mL (hypoparathyroidism) and ≥15 pg/mL (normal)." (PMID 28033305, 2016). "PTH also increases renal Mg re-absorption; thus hypomagnesaemic hypoparathyroidism may progress with increasing tetany below a threshold Mg level." (PMID 25138239, 2015). "The low serum calcium (Ca) (6.4 mg/dL; normal range, 8.8-10.3 mg/dL), high serum phosphate (7.2 mg/dL; normal range, 3.8-6.5 mg/dL) and inappropriately low serum parathyroid hormone (PTH) (7 pg/mL; normal range, 20-65 pg/mL) levels of the patient led to a diagnosis of hypoparathyroidism." (PMID 26316437, 2015). "However, some study series recommended abandoning the use of postoperative intact PTH alone for predicting postoperative hypoparathyroidism." (PMID 25691901, 2015). "Daily costs of synthetic PTH therapy prevented an indication for this therapy, although it is known that in hypoparathyroidism it is able to reduce daily requirements of calcium and vitamin D, of calciuria and of ectopic soft-tissue calcification, while improving bone health." (PMID 25348653, 2014). "Further work-up revealed hypoparathyroidism (Parathyroid hormone intact < 2.5 pg/ml." (PMID 18053182, 2007). "In addition, PTH level may be used as a quality marker allowing for estimation of the prevalence of early hypoparathyroidism and also to exclude a high prevalence of permanent postoperative hypoparathyroidism." (PMID 41229353, 2025). "Additionally, female is a risk factor for hypoparathyroidism after both total thyroidectomy and hemithyroidectomy with isthmusectomy, while higher hemoglobin levels and HDL-C are negatively correlated with the decline in PTH levels after total thyroidectomy." (PMID 40969367, 2025). "Finally, ChatGPT include recombinant PTH as a treatment option for hypoparathyroidism." (PMID 39881674, 2025). "Additionally, estrogen’s influence post-surgery could impact calcium regulation and facilitate parathyroid hormone recovery, potentially mitigating hypoparathyroidism even if glands are inadvertently removed." (PMID 40426871, 2025). "In any case, a very high proportion of patients with an immediate postoperative PTH value within the normal reference range after thyroid surgery would definitely be an indicator of adequate parathyroid sparing, as such patients hardly ever develop postoperative permanent hypoparathyroidism." (PMID 37995259, 2024). "In this study, we observed that the combined use of ICG and CNP, along with PTH test method, yielded significant improvements in identifying inferior parathyroid glands, preventing inadvertent dissection of parathyroid glands, and reducing postoperative temporary hypoparathyroidism." (PMID 38507176, 2024). "However, upon receiving the PTH results, our diagnosis was revised to hypoparathyroidism." (PMID 39328612, 2024). "Additionally, almost all patients who eventually developed permanent hypoparathyroidism had an immediate PTH level below the lower reference limit, or in occasional patients just above it, and as such follow-up may be concentrated on these patients." (PMID 37995259, 2024). "Hypoparathyroidism may increase the risk of hypercalciuria due to the lack of tubular calcium reabsorption by PTH." (PMID 38481445, 2024). "It is conceivable that, as it is already for bone regeneration, PTH may be a promising and novel therapeutic strategy for regulating different processes of skeletal muscle in those conditions in which there is muscle dysfunction due to hypoparathyroidism." (PMID 37189637, 2023).
hypoparathyroidism (continued). "Therefore, the low level of PTH in the current study raises the question of whether hypoparathyroidism could be involved in the etiology of laryngomalacia independently of the vitamin D level." (PMID 38813002, 2023). "Moreover, hypoparathyroidism is prevented by the expected secretion of PTH from the autograft." (PMID 37152972, 2023). "Hypoparathyroidism is a relatively rare disease characterized by deficient or absent production of PTH (with blood-serum PTH levels below the physiological reference range of 12–72 ng/L corresponding to 1.5–6.0 pmol/L), which leads to a disbalanced extracellular fluid calcium level." (PMID 37180074, 2023). "Further studies should aim to investigate if this potential renoprotective effect of PTH replacement therapy in hypoparathyroidism only applies to patients with an initial normal kidney function or also may be beneficial to patients with impaired kidney function." (PMID 34991581, 2022). "Notably, the ratio for patients with transient hypoparathyroidism among the three groups (postoperative PTH level, <1.3 pmol/L) was comparable (66.70%, 61.54%, and 63.16%), excluding the possibility that postoperative PTH levels affect the postoperative calcium levels." (PMID 36091150, 2022). "In addition, PTH therapy is administered in hypoparathyroidism, and hormone therapy is suggested as a high risk for ARONJ in this study because of its correlation with hypoparathyroidism." (PMID 35885858, 2022). "In some rare cases of autosomal dominant or recessive hypoparathyroidism, namely Familial Isolated Hypoparathyroidism, type 1 (FIH) (MIM 146200) patients present by heterozygous, homozygous, or compound heterozygous mutation in the PTH gene (11p15.3-p15.1) coding for the prepro-PTH peptide." (PMID 34068220, 2021). "While a diagnosis of hypoparathyroidism is supported in our patient by the borderline low serum calcium concentrations and a low level of parathyroid hormone, the patient did not have elevated serum phosphate levels, which would be expected in the face of a low parathyroid hormone level." (PMID 33840812, 2021). "Then, the recovery of post-operative serum PTH levels depended on both the in situ preserved PGs and autotransplanted PGs, and may be the in situ preserved PGs were the main barrier against permanent hypoparathyroidism." (PMID 34262932, 2021). "However, some vitamin D-deficient individuals do not exhibit increased PTH secretion, and this condition has been termed as ‘functional hypoparathyroidism’." (PMID 32821633, 2020). "PTH replacement is of value in lowering the doses of calcium and active vitamin D analogs required and may be of value in lowering long-term complications of hypoparathyroidism." (PMID 30540559, 2019). "Indeed, when we over-expressed FHL1b in human cells, we observed strong and significant increase in activation of the human PTH gene, confirming that FHL1 loss of function in the patient might well be the etiologic factor leading to hypoparathyroidism." (PMID 28444561, 2017). "At the time of examination (in average 8.2 years after surgery), 20 patients had normal PTH levels (48 %, mean 3.6 ± 1.9 pmol/l), eight patients had a mild hypoparathormonemia (19 %, mean 0.8 ± 0.4 pmol/l) and seven patients had a biochemical hypoparathyroidism (17 %)." (PMID 26467771, 2015). "His low PTH could be a consequence of his esophagus-colontransplant surgery, that is, his parathyroids may have been injured during the surgery ortheir blood supply compromised leading to hypoparathyroidism." (PMID 26425597, 2014). "For much of its history, hypoparathyroidism was considered unique among endocrine deficiencies in that it was not treated with hormone replacement, owing to limited understanding of parathyroid physiology and the absence of safe and effective PTH-based therapies." (PMID 41993986, 2026).
hypoparathyroidism (continued). "Outcomes included temporary hypoparathyroidism (THP), permanent hypoparathyroidism (PHP), and postoperative PTH, calcium (Ca), and vitamin D (VitD) levels." (PMID 40979704, 2025). "Laboratory tests revealed decreased serum calcium, elevated blood phosphorus levels, and reduced parathyroid hormone (PTH) levels, indicating the presence of "Hypoparathyroidism"." (PMID 40013314, 2025). "The high degree of satisfaction with TransCon PTH and its reported efficacy for hypoparathyroidism symptom management among patients who received the drug during the phase 3 study suggest that TransCon PTH may be an important and effective new treatment option for patients with hypoparathyroidism." (PMID 39136801, 2024). "In both Hypoparathyroidism and PHPT, PTH disturbances are correlated with neuropsychological symptoms, with a possible U-shaped curve." (PMID 37240884, 2023). "PTH values were either inappropriately normal or low in all hypocalcemic probands, consistent with ADH or hypoparathyroidism." (PMID 36970776, 2023). "No patients exhibited temporary hematoma or other complications following FNA, transient hypoparathyroidism occured in bilateral CLND and the incidence was 31.25% (25/80), serum parathyroid hormone returned to normal at post-operation one week or 2 months." (PMID 35733781, 2022). "While hypoparathyroidism is a common feature of KCS2, the PTH concentration in the serum of Fam111a−/− animals was similar to that in the Fam111a+/+ group." (PMID 35715480, 2022). "Therefore, hypoparathyroidism may be present even when PTH levels seem to be in the normal range." (PMID 36050906, 2022). "Parathyroid hormone (PTH) measurement within 45–120 minutes after the surgery is an indicator of both complete removal of the parathyroid adenoma and postoperative hypoparathyroidism." (PMID 34365979, 2021). "A very recent and well-conducted clinical study has shed light on the interdependent physiology of PTH and FGF-23 in patients with hypoparathyroidism." (PMID 34884774, 2021). "Animal studies also showed that PTH-null mice experienced high PO4 in spite of high circulating FGF-23, resembling participants with hypoparathyroidism in the present study." (PMID 32398014, 2020). "In the present study, the death of rats in the PTX-FC group, and undetectable postoperative PTH levels in all PTX group animals, demonstrated that this surgical method was highly effective and reproducibly generated an animal model of hypoparathyroidism." (PMID 27695051, 2016). "Consistent with this notion, removal of the PTH responsive region of the RANKL gene is sufficient to reduce the rate of bone resorption, mimicking the effects of hypoparathyroidism." (PMID 18698360, 2008). "In one study including four female patients with postsurgical hypoparathyroidism, s.c. injection of 100 μg GIP markedly reduced plasma CTX levels despite very low or undetectable PTH concentrations, indicating that its antiresorptive effect does not rely on PTH-mediated pathways." (PMID 41596254, 2026). "Previous studies have examined PTH measurements at various intervals (0 hours, 4 hours, 12 hours, 24 hours) primarily for diagnosing rather than predicting hypoparathyroidism." (PMID 40671592, 2026). "Our study found that age had no significant impact on postoperative hypoparathyroidism or relative postoperative PTH reduction." (PMID 40969367, 2025). "All patients exhibited PTH normalization within six months, with no permanent hypoparathyroidism cases." (PMID 40066709, 2025). "Unlike hypoparathyroidism, which is characterized by deficient PTH production, PHP is distinguished by elevated PTH levels despite normal vitamin D, magnesium, and renal function." (PMID 40125101, 2025). "In addition, postsurgical hypoparathyroid rats treated with AXT914 for 21 days continued to have elevations in serum calcium and PTH for 7 days after this calcilytic had been discontinued." (PMID 40086735, 2025).